ATR (ATR checkpoint kinase)
Diseases named in the same sentence as ATR in open-access papers (continued):
Sharing a sentence is not in itself a finding about the gene and the disease.
melanoma (continued). "We next investigated whether defective SPR in melanoma cell lines might be correlated with reduced ATR activity." (PMID 24416382, 2014). "Specifically, we will focus on PARP, ATM, CHK1, WEE1 and ATR inhibitors, for which preclinical data as single agents, taking advantage of synthetic lethal interactions, and in combination with chemo-targeted-immunotherapy, have been growing in melanoma, encouraging the ongoing clinical trials." (PMID 35563772, 2022). "In addition our overall data suggest that this characteristic NER defect is attributable to partial abrogation of ATR signaling, prompting speculation that ATR may constitute a haploinsufficient tumour suppressor for melanoma." (PMID 24416382, 2014). "The researchers irradiated ATR-mutant melanoma cell line with UVB and found defects in activation of ATR downstream targets such as CHEK1 phosphorylation and cell cycle arrest." (PMID 40940791, 2025). "BET inhibitors (RVX2135 or iBET762) in combination with ATRIs [Ataxia-telangiectasia and Rad3-related (ATR) is a kinase belonging to the PI3 kinase-like family; VE821 or AZ20], showed apoptosis effect on melanoma cells as well as the PDX model of melanoma." (PMID 36844227, 2023). "Recent preclinical evidence showed that the therapeutic combination of ATR and BET protein inhibitors is effective in melanoma, corroborating the same effects observed previously in MYC-induced lymphoma." (PMID 35563772, 2022). "The implication of ATM in melanoma development is recent, but the activation of the ATM/ATR pathway in response to UV-induced replication stress has been documented." (PMID 34262154, 2021). "Ataxia telangiectasia and Rad3 related (ATR) inhibitors have been reported to display synergism with JQ1 in the induction of apoptosis in lymphoma and melanoma cells." (PMID 30761268, 2019). "Upon LOXL3 depletion, melanoma cells display a faulty DNA damage response (DDR), characterized by ATM checkpoint activation and inefficient ATR activation leading to the accumulation of double-strand breaks (DSBs) and aberrant mitosis." (PMID 29229995, 2018). "By using cultured melanoma cells, patient-derived xenografts (PDXs) and syngenic transplant models we show that the therapeutic combination targeting of ATR and BET proteins is effective in melanoma." (PMID 28796244, 2017). "We therefore treated our three SPR-proficient melanoma strains with siRNA pools specifically targeting DNA-PKcs (DNA-PK catalytic subunit), ATM, ATR, or Chk1." (PMID 24416382, 2014). "Further integrative analysis revealed that patients harboring SBS7a had significantly elevated expression of DNA damage repair-related proteins, such as PRKDC, ATR, and POLD4, suggesting that elevated DNA damage repair contributes to poor prognosis in patients with melanoma." (PMID 39039072, 2024). "Interestingly, it was recently shown that prolonged ATR inhibitor treatment can abolish the antitumor immune responses in two murine cancer models (colorectal CT26 and melanoma B16-F10)." (PMID 37346039, 2023). "In addition, the phosphorylation levels of ATR, ATM, and BRCA1 were significantly increased after 4 Gy X-ray irradiation in B16 and S91 melanoma tumors." (PMID 37507394, 2023). "Compared to the ATR wild-type subjects, the number of macrophages and B cells increased noticeably, and the number of CD3+ T cells decreased in the immune infiltration of ATR mutant melanomas." (PMID 36071479, 2022). "A trial with 58 patients, including 34 melanoma patients, investigated the use of AZD6738, an oral inhibitor of the serine/threonine protein kinase ATR (Ataxia Telangiectasia and Rad3 Related) to treat refractory advanced solid tumors in combination with weekly paclitaxel." (PMID 33435389, 2021). "In melanoma cell lines, P22077 treatment remarkably activated the ATM/ATR signalling pathway." (PMID 34469054, 2021).
melanoma (continued). "This suggests that ATR is a good target in the context of TMZ treatment for tumor types beyond glioblastoma and advanced melanoma with specific molecular determinants that can be used to identify patients that might benefit from this combination." (PMID 34676045, 2021). "We demonstrate that HU effectively synergises with CHK1, but not ATR inhibition, in > 70% of melanoma and non‐small‐cell lung cancer cells assessed, resulting in apoptosis and complete loss of proliferative potential in vitro and in vivo." (PMID 31044505, 2019). "We have also shown that depletion of Chk1 does not influence UV photoproduct removal in melanoma cells, suggesting the participation of a substrate directly modified by ATR." (PMID 24416382, 2014). "The possibility that ATR-dependent phosphorylation of various substrates, including XPA and/or XPC, might regulate NER exclusively during S phase specifically in melanoma cells is currently under investigation." (PMID 24416382, 2014).
colorectal cancer (44 papers, 2008 to 2026). A primary or metastatic malignant neoplasm that affects the colon or rectum. "First, we applied a model of ATR-deficient DLD-1 human colorectal cancer cells to confirm synthetic lethality by using chemical POLA1 inhibition." (PMID 39128273, 2024). "ATR inhibitors are synthetically lethal in ARID1A-deficient human colorectal cancer and OCCC cell lines and xenograft models." (PMID 38275587, 2023). "Based on this concept, multiple studies demonstrated that colorectal cancer with deficient POLD1 activity possessed the increased sensitivity to ATR and CHK1 inhibitors in preclinical models." (PMID 35189839, 2022). "For example, among the 3504 colorectal cancer sample, 92 ATR residues are found to be mutated; in comparison, only 19 ATR residues were mutated among the 4850 prostate tumor samples." (PMID 33742106, 2021). "In general, the cancers with higher ATM or ATR mutation frequencies tend to have higher number of mutated residues; for example, endometrial cancer, non-Hodgkin’s lymphoma, and colorectal cancer, with an ATM mutation frequency of 8–10%, each has over 100 mutated residues." (PMID 33742106, 2021). "Various POLD1 variants have been found in colorectal cancer, but their significance as therapeutic targets for ATR pathway inhibition remains unknown." (PMID 33144657, 2020). "Genetic depletion of TTI1 destabilizes ATM and ATR, attenuates DNA damage signaling, impairs double-strand break repair, and sensitizes colorectal cancer cells to 5-fluorouracil and oxaliplatin." (PMID 42283915, 2026). "ATR activation has previously been found to be an effect of 5-aminosalicylic acid in colorectal cancer cell lines." (PMID 40986406, 2025). "While a recent study demonstrated BOLD-100’s modulation of the ATR signaling axis in colorectal cancer cells, our work represents the first in vivo validation of a BOLD-100 and ATR inhibitor combination regimen." (PMID 40514666, 2025). "Inhibition of ATR induced synthetic lethality in MMR-deficient cells and increased the effect of immunotherapy, in the CT26 colorectal cancer model." (PMID 40422251, 2025). "Taken together, these data would indicate that AhR directly regulates ATR/CHK1/γH2AX survival response in response to BOLD-100 treatment in BRAFMT colorectal cancer." (PMID 39083088, 2024). "Mechanistically, our study showed that the AhR controls BOLD-100 induced CYP1A1 levels, ROS production, and ATR activation in BRAFMT colorectal cancer cells." (PMID 39083088, 2024). "ARID1A loss of function is quite common, mostly among gynecological cancers, and renders the ATR pathway indispensable for ARID1A-deficient cells, as demonstrated in vitro and ex vivo in colorectal cancer (CRC) cells." (PMID 38474014, 2024). "To verify the synthetic lethal interaction between ATR and POLA1 we initially applied a well-described model of ATR-deficient DLD-1 human colorectal cancer cells." (PMID 39128273, 2024). "High-fat diets cause inhibition of checkpoint proteins through lysine homocysteinylation of ataxia-telangiectasia and Rad3-related protein (ATR) in mouse colorectal cancer models." (PMID 36038791, 2022). "Given the reported ability of ATM loss to sensitise to ATR/CHK1 inhibition, and our recent finding that ATM loss synergises with IGF axis inhibition, we also tested ATM-deficient SK-CO-1 colorectal cancer (CRC) cells." (PMID 34773074, 2022). "ATM can also protect colorectal cancer cells and lymphoblastoid cells from hydroxyurea-induced cell death, but seems less effective than ATR." (PMID 34685500, 2021). "VE-821 has been shown to be a potent ATR inhibitor by inhibiting phosphorylation of the ATR downstream target CHK1 at Ser345 in the colorectal cancer cell line HCT116." (PMID 32355263, 2020).
colorectal cancer (continued). "DNA IR-damage and cellular response via ATR, Epithelial to mesenchymal transition in colorectal cancer/Cellular senescence." (PMID 33240314, 2020). "Here, we applied a synthetic lethal screen directed against 288 DNA-repair genes using the well-defined ATR knock-in model of DLD1 colorectal cancer cells to identify potential DNA-repair defects mediating these effects." (PMID 26755646, 2016). "Following gene targeting of ATR in the human HCT116 colorectal carcinoma cell system, they found a significantly increased expression of DFS as well as other gross chromosomal rearrangements and amplifications." (PMID 19440510, 2008). "Taken together, our results indicate that combined BOLD-100 with ATR inhibition might represent a valuable targeting strategy for V600EBRAFMT colorectal cancer tumors." (PMID 39083088, 2024). "Taken together, these results would suggest that combined ATR inhibition/BOLD-100 treatment could result in objective responses in a clinical setting in BRAFMT colorectal cancer." (PMID 39083088, 2024). "In addition, ATR targeted siRNA combined with BOLD-100 resulted in significant increases in apoptosis in BRAFMT colorectal cancer cells." (PMID 39083088, 2024). "To investigate the exact regulatory role of PPP2R5A and the overall process of irinotecan‐activated ATM/ATR signalling, including phosphorylation and dephosphorylation, we exposed colorectal cancer cells to irinotecan for 1 h and then left the cells to recover for different time." (PMID 35187743, 2022). "Among the 46,588 tumor samples in the “curated set of nonredundant studies”, ATM and ATR are mutated in many different cancer types with the frequency ranging from ~1% for brain or testicular cancer to ~8–10% for endometrial, bladder, or colorectal cancer." (PMID 33742106, 2021). "Heterozygous mutations in ATR have been observed in microsatellite unstable human colorectal carcinomas further suggesting that ATR haploinsufficiency may play a role in tumourigenesis." (PMID 19440510, 2008). "Thus, siRNA-mediated POLA1 depletion induced similar effects as did ST1926 in ATR-deficient cells, further supporting our hypothesis of synthetic lethality between ATR and POLA1 in colorectal cancer cells." (PMID 39128273, 2024). "Implications: BOLD-100 induces BRAFMT-dependent replication stress, and targeted strategies against replication stress (e.g., by using ATR inhibitors) in combination with BOLD-100 may serve as a potential novel therapeutic strategy for clinically aggressive BRAFMT colorectal cancer." (PMID 39083088, 2024). "In particular, a study on colorectal cancer radiotherapy found that after treatment, cancer cells simultaneously upregulate CD47 and PD-L1 via the ATR-mediated DNA repair signaling pathway." (PMID 40909948, 2025). "Taken together, these data illustrate a synthetically lethal relationship between ATR and POLA1 through simultaneous impairment of ATR and POLA1 in DLD-1 colorectal cancer cells." (PMID 39128273, 2024). "In the current study, we found that treatment with BOLD-100 resulted in acute increases in ATR/CHK1 phosphorylation, in particular in colorectal cancer cells with activated/oncogenic BRAF signaling." (PMID 39083088, 2024). "In this review, we provide an overview of mechanisms, preclinical studies and advances in clinical trials of DNA-PKcs, ATM/ATR, CHK1/CHK2, WEE1 and PARP1 kinase inhibitors combined with radiotherapy for colorectal cancer treatment." (PMID 36230796, 2022).
colorectal cancer (continued). "In vitro studies indicate that ATR inhibitors can be used in combination with oxaliplatin, cisplatin, or CHK1 inhibitor to inhibit the proliferation of colorectal cancer cells." (PMID 34201502, 2021). "In the colorectal carcinoma cell line HCT 116, ARID1A is recruited to DSBs by its interaction with ATR where it sustains ATR activation and facilitates the generation of RPA coated single-strand DNA." (PMID 34737943, 2021). "Co-administration of ATR inhibition to BOLD-100 may therefore promote replication fork collapse and apoptosis in BRAFMT colorectal cancer." (PMID 39083088, 2024). "Notably, treatment with the ROS scavenger NAC attenuated BOLD-100-induced ROS as well as ATR/CHK1 phosphorylation levels and resulted in robust decreases in BOLD-induced apoptosis in BRAFMT colorectal cancer cells." (PMID 39083088, 2024). "To further investigate the possibility to take advantage of DDR to target acid-exposed cancer cells, we next examined the phosphorylation of ATM and ATR, and downstream checkpoint kinases CHK1 and CHK2 in colorectal cancer HCT116 cells cultured at pHe 6.5 or pHe 7.4." (PMID 38366255, 2024). "Also, we show that concomitant treatment with ATR inhibitors and BOLD-100 leads to marked increases in therapeutic efficacy in BRAFMT colorectal cancer." (PMID 39083088, 2024). "Indeed, ARID1A deficiency sensitises tumour cells to PARP inhibitors in breast cancer and colorectal cancer cells in vitro and in vivo, and this sensitivity is dependent on the interaction of ARID1A with ATR." (PMID 38275587, 2023). "The ATR-CHK1 axis of the DNA damage response is crucial for the survival of most colorectal cancer stem cells (CRC-SCs), but a significant fraction of primary CRC-SCs either is resistant to ATR or CHK1 inhibitors or survives the abrogation of the ATR-CHK1 cascade despite an initial response." (PMID 33921638, 2021). "Here, we found that quinacrine blocks the formation of TopBP1 condensates, inhibits ATR signaling, and improves the efficacy of 5-fluorouracil and irinotecan (mimicking the FOLFIRI combination used in the clinic) in a mouse model of peritoneal carcinomatosis from colorectal cancer." (PMID 41190242, 2025). "Of note, our data demonstrating increased sensitivity of ATR/CHK1 inhibitors in POLA1 depleted cells are strongly supported by already published data showing synthetic lethality between CHK1 and B-family DNA polymerase including POLA1 in both lung and colorectal cancer cells." (PMID 39128273, 2024). "We found that ATR inhibition abrogates BOLD-100 induced ATR/CHK1 activation, leading to synergistic decreases in cell viability and colony formation, in addition to robust increases in apoptosis when ATR inhibition was combined with BOLD-100 in BRAFMT colorectal cancer cells." (PMID 39083088, 2024). "Similar results have been observed in models of colorectal carcinomas treated with curaxins (small molecules that interfere with DNA-histone interactions), as well as in models of HPV-driven tumors responding to RT plus ATR serine/threonine kinase (ATR) inhibitors." (PMID 36319998, 2022).
glioblastoma (31 papers, 2011 to 2025). The most malignant astrocytic tumor (WHO grade IV). "Studies showed that NUSAP1 knockdown reduces the sumoylation level of ATR and cause DNA damage in glioblastoma multiforme cells." (PMID 35739489, 2022). "This study elucidates a potential mechanistic understanding of how the MMR system is involved in ATR activation by TMZ in glioblastoma cells, which is important for targeting MMR-mutated cancers." (PMID 35388070, 2022). "Klattenhoff found that the loss of NEIL3 enhanced sensitivity to ATR inhibitors in glioblastoma cells." (PMID 33921035, 2021). "Furthermore, high ATR expression is associated with poor survival in glioblastoma patients, and ATRi leads to reduced invasion of glioblastoma cells through dysregulated cytoskeletal networks." (PMID 38475864, 2024). "High ATR expression was associated with significantly poorer survival in clinical datasets while histological, protein expression, and spatial transcriptomics using glioblastoma tumor specimens revealed higher ATR expression at infiltrative margins." (PMID 37936324, 2024). "Recently published work from our laboratory showed that PARP and ATR inhibitors synergize in the common glioblastoma mutation in isocitrate dehydrogenase 1/2 (IDH1/2), so perhaps MMR-deficiencies may also benefit from this combination." (PMID 35388070, 2022). "This study suggests that for patients with NEIL3-deficient tumors, the combination of ATR inhibitors with olaparib may be useful in treating glioblastoma patients, which has significant clinical implications." (PMID 36497204, 2022). "In addition, another study demonstrated that loss of NEIL3 enhances sensitivity to ATR inhibitors in glioblastoma cells." (PMID 34591415, 2021). "Studies have demonstrated that inhibiting key DNA repair proteins, such as ATR, ATM, and DNA-PK, increases the susceptibility of glioblastoma cells to radiation-induced damage." (PMID 40652278, 2025). "Here, we report that inhibition of ataxia telangiectasia and Rad 3 related kinase (ATR) reduces invasion of glioblastoma cells through dysregulation of cytoskeletal networks and subsequent integrin trafficking." (PMID 37936324, 2024). "CDK18 knockdown or ATR inhibition, in glioblastoma stem-like cells (GSCs), suppressed HRD and conferred PARPi sensitivity." (PMID 38951876, 2024). "In vitro we demonstrate the efficacy of 2 separate ATR inhibitors, as well RNAi, in inhibiting glioblastoma cell motility." (PMID 37936324, 2024). "In glioblastoma, ATR inhibition has been explored in combination with poly-ADP ribose polymerase (PARP) inhibition or TMZ, showing synergistic interaction in vitro and in animal models." (PMID 38227740, 2024). "When compared to berzosertib, a widely used ATR inhibitor in clinical trials, gartisertib was 4-fold more potent across all glioblastoma cell lines (gartisertib median IC50 = 0.56 μM, berzosertib median IC50 = 2.21 μM)." (PMID 38227740, 2024). "Here, we examined the inhibition of ATR within 12 patient-derived glioblastoma cell lines using the potent ATR inhibitor, gartisertib, as a strategy to enhance standard treatment response." (PMID 38227740, 2024). "Nevertheless, our research provides additional evidence that inhibiting ATR sensitises a range of patient-derived glioblastoma cell lines to standard treatment and thus this approach is worthy of pursuing with ATR inhibitors that do penetrate the brain." (PMID 38227740, 2024). "Although relatively unexplored in glioblastoma, there lies potential to examine the effect of ATR inhibition as a strategy to increase immune recognition of the tumour." (PMID 38227740, 2024). "Although studied extensively in solid tumours, few studies have explored the combination of ATR inhibitors with radiation in glioblastoma, or with chemoradiation in great depth." (PMID 38227740, 2024). "Pharmacological inhibition with two different compounds and RNAi targeting of ATR opposed the invasion of glioblastoma, whereas overexpression of ATR drove migration." (PMID 37936324, 2024).